RN7SKP112 (RN7SK pseudogene 112)
Gene: Miscellaneous RNA gene on chromosome 2 (7,141,227 to 7,141,544, reverse strand). Ensembl gene ENSG00000223145.
Homologues: Orthologues: mouse Gm54537 (38% identical). Paralogues in human: RN7SKP79 (71% identical), 7SK (71% identical), RN7SKP6 (71% identical), RN7SKP176 (70% identical), RN7SKP273 (70% identical), RN7SKP90 (70% identical), RN7SKP30 (69% identical), RN7SKP203 (69% identical), RN7SKP255 (69% identical), RN7SKP71 (69% identical), RN7SKP170 (69% identical), RN7SKP180 (69% identical), and 284 more.